RNU6-948P (RNA, U6 small nuclear 948, pseudogene)
Gene: Small nuclear RNA gene on chromosome 4 (121,192,797 to 121,192,903, reverse strand). Ensembl gene ENSG00000252183.
Homologues: Orthologues: chimpanzee U6 (99% identical), macaque U6 (95% identical), guinea pig U6 (79% identical), mouse Gm22378 (73% identical). Paralogues in human: RNU6-1029P (84% identical), RNU6-1060P (84% identical), RNU6-1122P (84% identical), RNU6-41P (84% identical), RNU6-1019P (83% identical), RNU6-15P (83% identical), RNU6-199P (83% identical), RNU6-379P (83% identical), RNU6-1011P (82% identical), RNU6-1152P (82% identical), RNU6-116P (82% identical), RNU6-12P (82% identical), and 1285 more.